UCP1 (uncoupling protein 1)
Diseases named in the same sentence as UCP1 in open-access papers (continued):
Sharing a sentence is not in itself a finding about the gene and the disease.
diabetes (58 papers, 2009 to 2025). "The aim of this study is to evaluate the effect of single-nucleotide polymorphisms (SNPs) of the PPARGC1A and UCP1 genes on impaired fasting glucose (IFG) or type 2 diabetes mellitus (T2DM) and the haplotype-based interaction between these genes." (PMID 28591028, 2017). "The association between the UCPs genes and diabetes has been investigated by many studies, and the most often studied SNPs are the rs1800592 (−3826A/G) of the UCP1 gene, the rs659366 (−866G/A), rs660339 (Ala55Val), and Ins/Del of the UCP2 gene, and the rs1800849 (−55C/T) of the UCP3 gene." (PMID 32028915, 2020). "In summary, UCP1 and UCP2 have distinct roles in the regulation of mitochondrial-induced oxidative stress, a pathogenic factor in diabetes." (PMID 40149950, 2025). "In diabetics, the ratio of ω3/6 (1/1 to 1/5) improved insulin function by increasing the expression of uncoupling protein 1 in adipose tissue, decreasing FBS, cholesterol, TG, and LDL-c, and increasing glucose tolerance." (PMID 39133724, 2024). "Akr1c18 and Ucp1 are decreased dramatically in both Smad3 WT and Smad3 KO‐ db/db, indicating they are critical in diabetes‐related renal injury." (PMID 33369170, 2021). "Both UCP1 KI pigs and WT controls had similar body weight and developed a comparable degree of diabetes mellitus and hypercholesterolemia (DMHC) after 12 months of HFHC diet." (PMID 34878840, 2021). "Strategies for combating metabolic diseases through the activation of UCP1 have been proposed; for instance, eight subjects with diabetes reported a 43% increase in insulin sensitivity when UCP1 was activated by cold acclimation (14–15 °C) for 10 days." (PMID 31590292, 2019). "Multiple regression analysis showed that age, BMI, LVEF, EAT UCP1 expression and diabetes were independent predictors of PGC1α mRNA levels in EAT." (PMID 27542888, 2016). "At multiple regression analysis, age, body mass index, left ventricular ejection fraction, UCP1 expression of epicardial adipose tissue and diabetes came out to be independent predictors of PGC1α levels." (PMID 27542888, 2016). "To conclude, UCP1 is an excellent target to struggle diabetes and decrease body fat mass, improving whole metabolism." (PMID 25688211, 2015). "Markedly reduced expression of uncoupling protein-1 (Ucp-1, 98% reduction in expression) is consistent with diabetes-induced mitochondrial dysfunction." (PMID 24827579, 2014). "UCP1 is considered to be a candidate gene for diabetes because of its role in thermogenesis and energy expenditure." (PMID 23841103, 2013). "As UCP1 has recently been found to play important roles in ROS production in diabetes, we hypothesized that PCA treatment may inhibit ROS production through upregulating UCP1, which would need further validation in future studies." (PMID 37025617, 2023). "Similarly, the T2DM (type 2 diabetes mellitus) rats supplemented with mulberry leaf demonstrated brown adipocytes and elevated expressions of UCP1 protein in BAT." (PMID 37686745, 2023). "Accelerated metabolism in skeletal muscle by uncoupling activity due to UCP1 expression may also delay age-related diseases such as diabetes, hypertension, atherosclerosis, and cancer." (PMID 35323702, 2022). "Interestingly, the beneficial effect of bone marrow fat on the regulation of bone mass is presented through the expression of brown adipocyte gene markers (Ucp1, Prdm16), and this ability diminishes with a decrease in metabolic capacity due to age or diabetes." (PMID 35733771, 2022). "Although three SNPs of UCP1 were associated with DR in participants of poor glucose control, and one SNP of UCP3 was found to be associated with DR in diabetes patients with well controlled hyperglycemia, the significance did not remain after Bonferroni correction was applied." (PMID 32028915, 2020).
diabetes (continued). "Therefore, to examine the significance of UCP1 activity for the diabetes-ameliorating effect of β3-agonist treatment, the effect of CL-316,243 treatment was investigated in mice made prediabetic." (PMID 28580291, 2017). "Although recent studies indicate that epicardial adipose tissue expresses brown fat-like genes, such as PGC1α, UCP1 and PRDM16, the association of these genes with type 2 diabetes mellitus (DM2) in coronary artery disease (CAD) remains unknown." (PMID 27542888, 2016). "Several gene polymorphisms of UCP1, UCP2, and UCP3 were reported to be associated with diabetes." (PMID 23841103, 2013). "Some interactions with a nominal p≤0.01 were found between sex and SNPs in the UCP1 and UCP3 gene; between smoking, diabetes, hypertension and SNPs in UCP5 and SIRT5; and between SNPs in the UCP5 gene and the UCP1, SIRT1, SIRT3, SIRT5, and SIRT6 genes in association with plaque phenotypes." (PMID 22087257, 2011). "Therefore, we sought to determine whether hyperbaric oxygen would ameliorate insulin sensitivity by promoting glucose transporter type 4 (GLUT4) expression in muscle and by stimulating UCP1 in brown adipose tissue (BAT) in a streptozocin (STZ)-induced type 2 diabetes mellitus (T2DM) mouse model." (PMID 32082261, 2020). "The progress in the role of UCP1, UCP2, and UCP3 on diabetes mellitus is summarized in this review." (PMID 23841103, 2013). "It has been reported that obese humans with diabetes have less ucp1 in sWAT than obese humans without diabetes, suggesting brown-like characteristics of sWAT are protective." (PMID 23241754, 2012). "A central question is whether reduced PGC1α and UCP1 mRNA expression in EAT is a prelude to the development of DM2 through a constitutively lower rate of β-oxidation and lower adipose activation, or a consequence of the diabetes itself, in either case leading to increased severity of CAD." (PMID 27542888, 2016).
type 2 diabetes (50 papers, 2009 to 2026). "Another research of 570 Japanese subjects found that, the rs10011540 and Met229Leu polymorphisms of UCP1 are in LD, and they are associated with type 2 diabetes." (PMID 32028915, 2020). "The rs10011540 and rs3811787 of the UCP1 gene was marginally significantly associated with DR in Chinese type 2 diabetes patients." (PMID 32028915, 2020). "A study including1800 Asian Indians indicated that a haplotype, the -3826A/ -122C/−Met of UCP1, is a genetic risk for developing type 2 diabetes." (PMID 32028915, 2020). "A significant association of UCP1 polymorphisms rs1800592 [OR, 1.52 (1.10–2.08); p = 0.009] was observed in the obese cohort after adjusting with age, sex and type 2 diabetes." (PMID 30458724, 2018). "In contrast, other investigations—particularly those including patients with type 2 diabetes—have demonstrated reduced UCP-1 expression, pointing to a loss of brown-like adipose characteristics and a possible adverse impact on metabolism and disease progression." (PMID 41294813, 2025). "It is reported that dietary safflower oil, which is rich in the linoleic acid, reduced trunk adipose mass and increased total body lean mass in obese women with type 2 diabetes and was associated with gene expression of uncoupling protein (UCP) 1 and UCP content in the adipose tissue of rats." (PMID 28540308, 2017). "In conclusion, the present study indicated that the rs10011540 of the UCP1 gene is marginally significantly associated with DR, and rs3811787 is marginally significantly associated with STDR in Chinese type 2 diabetes patients." (PMID 32028915, 2020). "Ucp1-ablated mice are obese and have type 2 diabetes, though this only occurs when living at thermoneutrality." (PMID 29206867, 2017). "It regulates energy balance, increases adipocyte Uncoupling Protein-1 (UCP1) expression, improves insulin sensitivity, and contains the spread of variable metabolic diseases, including obesity, type 2 diabetes mellitus (T2DM), and hypertension." (PMID 35094663, 2022).
Cachexia (28 papers, 2011 to 2026). Severe weight loss, wasting of muscle, loss of appetite, and general debility related to a chronic disease. "Lactate infusion also enhanced adipose UCP1 expression in mice assessed by immunohistochemical staining, recapitulating adipose UCP1 upregulation in the patients with cancer-associated cachexia." (PMID 38499763, 2024). "Several studies have implicated the activation of (BAT) in the pathogenesis of cancer-associated cachexia owing to the increased activity of uncoupling protein 1 (UCP-1)." (PMID 37998333, 2023). "In particular, cachexia and low Ucp1 expression in brown and white adipose tissue were associated with increased inflammation in the central nervous system and in the periphery and with anemia and changes in circulating testosterone levels." (PMID 35454855, 2022). "These enzymes, along with thermogenic proteins (e.g., Ucp1, Sln, Ryr1 and Atp2A1) may be targetable to mitigate cachexia‐related fat loss." (PMID 40468964, 2025). "However, the precise role of UCP1 in disease-associated cachexia in humans is still a topic of debate." (PMID 36499637, 2022). "WAT browning, characterized by increased beige adipocyte number and UCP1 expression, accelerates energy expenditure and exacerbates cachexia progression." (PMID 39727925, 2024). "IL-6 also plays an important role in mediating BAT activation by increasing the expression of UCP1 and activating fatty acid β-oxidation related gene thermogenesis in gastric cancer and colon cancer patients with cachexia." (PMID 37205195, 2023). "Treating mice with the selective β3-AR antagonist ameliorates cachexia and decreases UCP1 levels in subcutaneous WAT." (PMID 37205195, 2023). "During cachexia progression, WAT browning is associated with lipid mobilization and increase of the expression of Uncoupling protein 1 (UCP-1), also called thermogenin, contributing in this way to the dissipation of energy through heat production." (PMID 36158184, 2022). "Evidences from mouse model of pancreatic cancer suggest that adipose browning precedes adipose tissue wasting and, consistently, expression of UCP1 and body temperature are both increased in pancreatic cancer patients before cachexia manifestation." (PMID 36158184, 2022). "Intercommunication between cancer and adipose tissues involves UCP1-regulated energy expenditure, which leads to fat wasting in cachexia, and, in this context, VA treatment has induced UCP1 activity." (PMID 32722030, 2020). "It has been reported that activation of BAT (via increased Ucp1 expression) contributed to the development of cachexia in mice with colon cancer cell line implantations." (PMID 31069007, 2019). "In the present study, LLC-induced cachexia resulted in a consistent browning phenotype (morphology) of scAT followed by a marked upregulation of Ucp1 levels." (PMID 30575787, 2018). "Thus, Ucp1-independent mechanisms, such as increased lipolysis or decreased lipogenesis, have been suggested to also contribute to cachexia." (PMID 40964365, 2025). "The author concluded that the expression of UCP-1 increases in the early stage of cachexia, which may be due to sympathetic modulation." (PMID 36900198, 2023). "In addition, Western blot analysis demonstrated that in adipose tissue, the expression of UCP-1, the key rate-limiting enzyme in fat degradation, was significantly increased in the adipose tissue of mice in the cachexia group." (PMID 36569317, 2022). "Nevertheless, in vivo studies in CKD mice have recently pointed out that SHPT may promote adipose tissue browning and muscle wasting, through stimulation of thermogenic gene expression, and more precisely of uncoupling protein-1 (Ucp1), ultimately leading to cachexia." (PMID 34458210, 2021). "In this regard, we observed decreased Ucp1 gene expression in BAT and WAT of mice with mild cachexia, recapitulating a previous study." (PMID 40237521, 2025).
Cachexia (continued). "Both murine models and patients with cachexia have shown an increase in UCP2 and UCP3 proteins in skeletal muscles and an increase in UCP1 in brown adipose tissue." (PMID 38791998, 2024). "The same kind of result was obtained by another study on pancreatic cancer cachexia, which showed a reduction in UCP-1 expression in BAT and WAT with the progression of cachexia." (PMID 36900198, 2023). "Interleukin-6 inhibits the synthesis of lipids in adipocytes and drives the expression of UCP-1, which is important for the WAT to BAT shift occurring in cachexia, responsible for the increased energy expenditure." (PMID 32660156, 2020). "Furthermore, IL-6 has been shown to inhibit the synthesis of lipids in adipocytes and drives the expression of UCP-1, which is important for the WAT to BAT shift occurring in cachexia, responsible for the increased energy expenditure." (PMID 32660156, 2020). "Furthermore, in addition to human studies, the upregulation of markers indicative of BAT, such as PR domain zinc finger protein 16 (PRDM16) and uncoupling protein 1 (UCP1), could also be elucidated in the C26-induced cachexia murine model." (PMID 38791998, 2024). "Similarly, the expression levels of the FFA β-oxidation gene carnitine palmitoyltransferase (Cpt1) and browning of WAT markers, including Cd137, Zic-1 and UCP-1, were increased compared with rats without cachexia in the control group (P < 0.01)." (PMID 36670439, 2023). "In particular, data showed that an AMP-activated protein kinase (Ampk)-stabilizing peptide determined the amelioration of adipose tissue wasting interfering with CIDEA pathways independently of UCP1; moreover, the absence of UCP1 did not protect against the development of cachexia in mice." (PMID 35454855, 2022). "In addition, compared with cancer patients without cachexia, the expression of UCP1 in adipose tissue of CAC patients is higher, which may lead to adipose tissue atrophy and more heat production." (PMID 37205195, 2023).
Hepatic steatosis (28 papers, 2014 to 2025). Steatosis is a term used to denote lipid accumulation within hepatocytes. "Conversely, UCP1 knockout (KO) mice have an increased susceptibility to the adverse effects of a high fat (HF) diet and are prone to glucose intolerance and hepatic steatosis." (PMID 34829779, 2021). "However, IGF2BP2-deficient mice show remarkable resistance to the diet-induced fatty liver via enhancing the expression of mRNAs encoding mitochondrial proteins, such as uncoupling protein-1 (UCP1)." (PMID 37020540, 2023). "In this study, we investigated the protective effects of EPA in attenuating hepatic steatosis induced by HF diet and UCP1 KO by assessing mitochondrial and peroxisomal hepatic lipid oxidation as well as mitochondrial metabolic futile cycling." (PMID 34829779, 2021). "In the males, supplementation with EPA prevented hepatic steatosis in the UCP1 KO mice independently of body weight." (PMID 34829779, 2021). "UCP1 KO exacerbated HF diet-induced liver steatosis in a thermoneutral environment, but only in the male mice." (PMID 34829779, 2021). "Overall, our data suggest sex-dependent effects of both UCP1 KO and HF-diet induced hepatic steatosis and rescue with EPA supplementation." (PMID 34829779, 2021). "Inhibition of the upstream regulator (IL-6) and the downstream regulator (UCP-1) of burn-induced browning protected mice from the development of hepatic steatosis." (PMID 31740668, 2019). "To directy link WAT browning to the development of hepatic steatosis after a burn injury, we sought to block the two main regulators, IL-6 and UCP-1, involved in post-burn WAT browning." (PMID 31740668, 2019). "Together, these findings provide compelling evidence that inhibition of burn-induced browning via the deletion of either the upstream or downstream regulators, IL-6 and UCP-1, respectively, attenuates burn-induced hepatic steatosis." (PMID 31740668, 2019). "Oral KRGM-gintonin also alleviated fatty liver, reduced plasma triacylglycerol and cholesterol levels, and promoted the expression of thermogenesis-related genes, including uncoupling protein-1 (UCP1) and hormone-sensitive lipase (HSL), specifically in brown adipose tissue." (PMID 41374084, 2025). "There are three main mechanisms involved in the improvement of hepatic steatosis during aerobic activity: activation of lipolysis in different tissues, upregulation of uncoupling protein-1 and peroxisome proliferator-activated receptor γ pathways, and alteration of adipokine levels." (PMID 39683618, 2024). "Pure calorie-restrictive diets may lead to changes in serum bile acid profiles and gut microbiota, with associated down-regulation of uncoupling protein 1 (UCP1), an important regulator of energy expenditure; weight rebound; and liver steatosis." (PMID 39796579, 2024). "Moreover, studies conducted in UCP1 KO mice challenged with severe thermal injury have shown the promising impact of reducing thermogenesis in the prevention of hepatic steatosis and metabolic dysfunction." (PMID 34185433, 2021). "In addition, metformin also alleviated adiposity and hepatic steatosis, and greatly upregulated uncoupling protein 1 (UCP1) expression in adipose tissues of DIO mice." (PMID 34483906, 2021). "Thus far having shown that removing genes (IL-6, UCP-1) involved in post-burn WAT browning protected mice from hepatic steatosis, we wanted to determine if we could attenuate this adverse post-burn response therapeutically in wild type mice." (PMID 31740668, 2019). "Similar to GDF15, FGF21 reduces the body weight through a non-adipose tissue effect; increases insulin sensitivity, adaptive thermogenesis, and uncoupling protein 1 (UCP1)-independent EE; and reverses hepatic steatosis." (PMID 33718833, 2021). "Conversely, both UCP1−/− and IL-6−/− mice that were protected from both burn-induced WAT browning and hepatic steatosis, also showed reductions in hepatic ER stress." (PMID 31740668, 2019).
Hepatic steatosis (continued). "Deletion of interleukin 6 (IL-6) and the uncoupling protein 1 (UCP1), regulators of burn-induced WAT browning completely protected mice from hepatic steatosis after the injury." (PMID 31740668, 2019). "Therefore, it is possible that LBP activating or elevating the expression of UCP-1 and PGC-1α would have crucial effect on increasing the energy expenditure to ultimately prevent fatty liver, which in turn protects liver function." (PMID 25013763, 2014). "Moreover, restoration of hepatic ApoA5 or activation of UCP1 in brown adipose tissue (BAT) by cold exposure or CL316243 administration could significantly correct sHTG and hepatic steatosis in ApoA5-/- hamsters." (PMID 38505614, 2024). "We believe that improvement in mitochondrial function and browning (evidenced by UCP1 and PGC1A upregulation) of white fat may have helped to reduce the systemic inflammation (as seen with TNFα plasma values reduction) with subsequent ameliorating of fatty liver disease." (PMID 31477174, 2019). "To further implicate WAT browning in post-burn hepatic steatosis, we next utilized UCP-1 KO (UCP-1−/−) mice in which the downstream regulator of post-burn WAT browning, namely, UCP-1 is not expresed." (PMID 31740668, 2019).